HES1 (hes family bHLH transcription factor 1)
Description:
Transcriptional repressor of genes that require a bHLH protein for their transcription. May act as a negative regulator of myogenesis by inhibiting the functions of MYOD1 and ASH1. Binds DNA on N-box motifs: 5'-CACNAG-3' with high affinity and on E-box motifs: 5'-CANNTG-3' with low affinity (By similarity). May play a role in a functional FA core complex response to DNA cross-link damage, being required for the stability and nuclear localization of FA core complex proteins, as well as for FANCD2 monoubiquitination in response to DNA damage.
Synonyms: bHLHb39; hHL; HRY; FLJ20408; HES-1
Tractability: PROTAC: UniProt records ubiquitination sites on it; ubiquitination databases record sites on it.
Target class: Transcription factor
Gene: Protein-coding gene on chromosome 3 (194,136,142 to 194,138,732, forward strand). Ensembl gene ENSG00000114315.
Subcellular location: Nucleus
Subcellular location (Human Protein Atlas): Nucleoplasm
Pathways (Reactome):
Signal Transduction: NOTCH1 Intracellular Domain Regulates Transcription; NOTCH2 intracellular domain regulates transcription; NOTCH3 Intracellular Domain Regulates Transcription; NOTCH4 Intracellular Domain Regulates Transcription
Disease: Constitutive Signaling by NOTCH1 HD+PEST Domain Mutants; Constitutive Signaling by NOTCH1 PEST Domain Mutants
Gene expression (Transcription): RUNX2 regulates osteoblast differentiation; RUNX3 regulates NOTCH signaling
Developmental Biology: Regulation of gene expression in late stage (branching morphogenesis) pancreatic bud precursor cells
Gene Ontology:
Molecular function: histone deacetylase binding; protein binding; sequence-specific double-stranded DNA binding; DNA binding; DNA-binding transcription factor activity, RNA polymerase II-specific; DNA-binding transcription repressor activity, RNA polymerase II-specific; E-box binding; N-box binding; protein homodimerization activity; RNA polymerase II-specific DNA-binding transcription factor binding; sequence-specific DNA binding; chromatin binding; DNA-binding transcription repressor activity; HLH domain binding; identical protein binding; JUN kinase binding; protein dimerization activity; protein-containing complex binding; protein-folding chaperone binding; transcription corepressor binding
Biological process: negative regulation of DNA-templated transcription; negative regulation of pro-B cell differentiation; negative regulation of stem cell differentiation; negative regulation of transcription by RNA polymerase II; neuronal stem cell population maintenance; Notch signaling pathway; anterior/posterior pattern specification; artery morphogenesis; ascending aorta morphogenesis; embryonic heart tube morphogenesis; forebrain radial glial cell differentiation; negative regulation of forebrain neuron differentiation; negative regulation of glial cell proliferation; negative regulation of neuron differentiation; negative regulation of oligodendrocyte differentiation; nervous system development; outflow tract morphogenesis; pharyngeal arch artery morphogenesis; positive regulation of astrocyte differentiation; positive regulation of cell population proliferation; positive regulation of DNA binding; positive regulation of mitotic cell cycle, embryonic; positive regulation of receptor signaling pathway via JAK-STAT; positive regulation of transcription by RNA polymerase II; positive regulation of tyrosine phosphorylation of STAT protein; and 35 more
Cellular component: nucleoplasm; nucleus; chromatin; cytoplasm; nuclear matrix; protein-containing complex
Genetic constraint (gnomAD): Loss-of-function variants: 6 observed, 19.52 expected, observed/expected ratio (o/e) 0.31, 90% interval 0.17 to 0.61. The upper end of that interval is the gene's LOEUF score, 0.61, which puts it in group 2 of 6, group 1 being the genes least tolerant of losing a copy. Missense variants: 335 observed, 357.97 expected, observed/expected ratio (o/e) 0.94, 90% interval 0.86 to 1.02. Synonymous variants: 167 observed, 151.05 expected, observed/expected ratio (o/e) 1.11, 90% interval 0.97 to 1.26.
Homologues: Orthologues: chimpanzee HES1 (100% identical), macaque HES1 (100% identical), pig HES1 (99% identical), rabbit HES1 (99% identical), guinea pig HES1 (99% identical), rat Hes1 (99% identical), mouse Hes1 (98% identical), zebrafish her6 (76% identical), tropical clawed frog hes1 (75% identical), Drosophila melanogaster E(spl)mgamma-HLH (21% identical), Drosophila melanogaster E(spl)m7-HLH (20% identical), Drosophila melanogaster E(spl)mbeta-HLH (20% identical), and 6 more. Paralogues in human: HES4 (46% identical), HEY2 (25% identical), HES2 (24% identical), HEY1 (24% identical), HEYL (23% identical), BHLHE41 (22% identical), BHLHE40 (22% identical), HES5 (20% identical), HES3 (19% identical), HELT (19% identical), HES6 (19% identical), HES7 (19% identical).
Diseases named in the same sentence as HES1 in open-access papers:
HES1 is named in the same sentence as 278 diseases in open-access papers, as found by Europe PMC text mining. Sharing a sentence is not in itself a finding about the gene and the disease. The quoted sentences say what the papers report.
breast carcinoma (67 papers, 2009 to 2026). "The silencing of NUMB in primary normal breast cells results in a significant increase in Hes-1 mRNA, and the aberrant activation of Notch signaling in human breast cancers was thought to be due to the loss of NUMB expression." (PMID 35457181, 2022). "Interestingly, the HES1 pathway is essential for the maintenance of TIC in breast cancer cells and has been associated with metastasis and multidrug resistance." (PMID 33772015, 2021). "Mechanistically, Notch signaling upregulates Hes1 to orchestrate T-cell development and influences T-cell responses in breast cancer, suggesting its potential as an immunotherapeutic target." (PMID 40755759, 2025). "In breast cancer, elevated Hes1 mRNA correlates with tamoxifen (TAM) resistance, advanced N stage, and nipple involvement, suggesting its role in endocrine therapy failure." (PMID 40755759, 2025). "Hes1 regulates breast cancer cell proliferation, EMT, and invasion through multiple pathways such as Notch, AKT, STAT, and HIF-1α." (PMID 40755759, 2025). "Of note is the group of genes SP1, MYC, HEY2, E2F1, E2F2, and HES1, which are known to be associated with the KEGG breast cancer functional pathway." (PMID 40724805, 2025). "Mechanistically, Hes1 maintains the stemness of breast cancer stem cells (BCSCs) by directly activating Slug transcription, thereby enhancing the aggressiveness and treatment resistance of TNBC." (PMID 40755759, 2025). "In breast cancer, imatinib inhibits the acetyltransferase activity of p300, leading to decreased levels of H3K18Ac and H3K27Ac, thereby downregulating Hes1 expression and inhibiting EMT." (PMID 40755759, 2025). "Mechanistically, Hes1 activates Slug to enhance breast cancer stemness via the Hes1/Slug/EMT axis, further linking stemness to therapeutic resistance." (PMID 40755759, 2025). "This regulatory axis manifests in breast cancer through Hes1-mediated PTEN suppression and AKT hyperactivation, driving tumor survival and invasion." (PMID 40755759, 2025). "In vitro experiments have confirmed that knocking down Hes1 can inhibit hypoxia-induced breast cancer cell proliferation and invasion." (PMID 40755759, 2025). "In contrast, downregulation of NOTCH1 decreases HES1 activity, which predicted the inhibition of the bio-functions: migration of tumor cells and invasion of breast cancer cells." (PMID 38337803, 2024). "Another carotenoid, lutein, seems to suppress the EMT in hypoxic conditions via the hairy and enhancer of split 1 (HES1) pathway in breast cancer cells." (PMID 39199148, 2024). "The results revealed that the expression of Hes1 and Hey1 was upregulated in colorectal and breast cancer cell lines." (PMID 37686467, 2023). "HES1 overexpression in breast cancer is correlated with advanced stage, node metastasis, negative estrogen receptor expression, and triple-negative status." (PMID 35163327, 2022). "In triple-negative cancer, HES1 functions as an oncogene, and promotes breast cancer stem cells stemness properties via targeting SLUG." (PMID 35163327, 2022). "Our previous study also found that HES1 is highly expressed in TNBC than in other subtypes of breast cancer and significantly correlated with advanced TNM stage and poor prognosis." (PMID 33390847, 2021). "Based on these, our previous reported study has demonstrated that HES1 expression is significantly high level in TNBC compared with other subtypes of breast cancer and HES1 leads to EMT process and promotes invasion." (PMID 33390847, 2021). "Along this line, Hes1 exhibits an oscillatory behavior in breast cancer cells and a relationship between Hes1 dynamics and the cell-cycle was found such that in most cells, division takes place at or near the peak of Hes1 expression." (PMID 33920095, 2021). "Meanwhile, Notch signaling was reactivated in senescent breast cancer cells (Co-SEN-MCF-7), which was accompanied by the downregulation of N1ICD and HES1, after direct co-culture with breast cancer cells." (PMID 33467780, 2021).
breast carcinoma (continued). "The expression of NICD and Hes1 was also reduced in EpCAM+ breast cancer cells from PyMT;Zeb1cKO mice compared with that from PyMT mice." (PMID 33046710, 2020). "HES1 was recently shown to have a prominent role in proliferation and invasion of breast cancer cells, and its silencing led to downregulation of p-Akt signaling and ultimately prevented EMT." (PMID 32655837, 2020). "More importantly, HIF1α has been reported to induce drug resistance through the hairy and enhancer of split-1 gene (HES1) in breast cancer." (PMID 32972441, 2020). "Notch signalling pathway affected the proliferation of breast cancer by affecting its downstream gene HES‐1, and regulated the migration of breast cancer cells by affecting the expression of EMT pathway." (PMID 30809937, 2019). "It has been reported that E2 induced the recruitment of N1ICD to the Hes-1 promoter in breast cancer cells, and that Notch1 regulated expression levels of ERα in ER-positive breast cancer." (PMID 31122254, 2019). "While previous studies have shown that both Hes1 and Hey1 are sensitive Notch target genes, Hey is more sensitive than Hes gene for Notch pathway inhibition in breast cancer." (PMID 25645291, 2015). "Our data showed that the expression of the Notch signaling downstream genes Hes1 and Hey1 decreased in breast cancer cells with Notch1 inhibition." (PMID 25645291, 2015). "γ-secretase mediated downregulation of Notch signaling followed by reduction in Notch1 downstream products like Hes1 and cyclin D1 by 6-shogaol thus explain its efficacy in breast cancer spheroid cells." (PMID 26355461, 2015). "Consistent with one study that As2O3 inhibited Notch-1 and its target gene Hes-1 in gliomas, we found that As2O3 down-regulated the expression of Notch-1 and its target genes in breast cancer cell lines." (PMID 22949821, 2012). "Hes1 is a target of Notch1 signaling, which is aberrantly activated in a variety of human cancers, including prostate, lung, colorectal, osteogenic, and breast carcinomas." (PMID 21106062, 2010). "Culture of other breast cancer cells under hypoxia also increased the expression of HES1 and HEY1 to different degrees, except for SK-BR-3 cells, which did not have an elevated HES1 expression under hypoxic conditions." (PMID 20010940, 2010). "We therefore suggest that E2 treatment of ERα+ breast cancer cells leads to inactivation of Hes-1, both directly and through the induction of Hes-6." (PMID 19891787, 2009). "We previously identified and characterized Hes-1 as an essential transcription factor in ERα-signaling and a strong inhibitor of estrogen-stimulated proliferation in breast cancer cells." (PMID 19891787, 2009). "We earlier identified E2F-1 as a crucial transcription factor directly inhibited by Hes-1 at the transcriptional level in breast cancer." (PMID 19891787, 2009). "We detected the presence of active, cleaved Notch1, along with downstream targets of the Notch pathway, Hes1/Hes5, in ~75% of breast cancers, clearly indicating that in a large proportion of breast cancers Notch signaling is aberrantly activated." (PMID 20030805, 2009). "As many as 75% of breast cancers showed accumulation of cleaved Notch1 (27/35) and expression of Hes1/5 (27/36)." (PMID 20030805, 2009). "We showed previously that Hes-1 represses the proliferation of breast cancer cells and that E2F-1 is directly inhibited by Hes-1 at the transcriptional level." (PMID 19891787, 2009). "Immunohistochemical analysis of 150 primary breast cancer specimens revealed weak nuclear expression of Hes1 in 5 cases of ductal carcinoma in situ (DCIS), while its expression was significantly upregulated in 53 cases of invasive ductal carcinoma (IDC) (35.3%)." (PMID 40755759, 2025).
breast carcinoma (continued). "For example, in colon and breast cancers, Hes1 overexpression downregulates epithelial markers (e.g., E-cadherin) and upregulates mesenchymal markers (N-cadherin, vimentin), thereby inducing EMT and accelerating tumor proliferation, invasion, metastasis, and drug resistance." (PMID 40755759, 2025). "The AhR has been reported to induce Hes1 expression in mammary carcinoma and liver cells." (PMID 39201457, 2024). "In addition to the effect of IS, direct upregulation of Hes1 expression through the AhR, independent from Notch, was observed in human mammary carcinoma cells." (PMID 39201457, 2024). "HES1 (hairy and enhancer of split homolog-1), a transcriptional repressor involved in cell differentiation and proliferation as well as in cancer development, is overexpressed in breast cancer and especially in TNBC." (PMID 35163822, 2022). "Next, an in silico analysis showed that genes related to breast cancer, including HES1, MYC, CCND1, FOS and PGR, could be regulated by NRIP1 (data not shown)." (PMID 34707101, 2021). "Our results revealed a significant upregulation of cleaved, active Notch1 intracellular domain (N1ICD) and canonical Notch1target HES1 in adjacent breast cancer cells (Co-MCF-7-mRFP) of SEN-MCF-7, compared with that in MCF-7-mRFP cultured with senescence culture medium (SEN-CM-MCF-7-mRFP)." (PMID 33467780, 2021). "6-shogaol treatment in breast cancer cells results in the suppression of proliferation by the significant induction of apoptosis and the inhibition of autophagy by the regulation of the Notch signaling pathway (Hes1 and CyclinD1 genes)." (PMID 34575981, 2021). "In addition, the Si-STAT3 transfection reduced the relative mRNA expression of JAG1 and HES1 in linc00514-OVE breast cancer cells." (PMID 32943090, 2020). "Therefore, we suggest that Nrf2 controls cell proliferation in breast cancer through influencing Notch1 and affecting HES‐1." (PMID 30809937, 2019). "Interestingly, both HES1 and HEY1 have been implicated as part of the hypoxic response associated to breast cancer progression." (PMID 23826634, 2013). "Because Hes-6 antagonizes Hes-1, our hypothesis is that Hes-6 increases the proliferation of breast cancer cells and is regulated by estrogen." (PMID 19891787, 2009). "In breast cancer cells, downregulation of Hes-1 is essential for estrogen-mediated proliferation." (PMID 19891787, 2009). "In T47D and MCF-7 breast cancer cells, ERα promotes proliferation by stimulating expression of cell-cycle regulators and through downregulation of the transcriptional repressors, such as Hes-1." (PMID 19891787, 2009). "Furthermore, additional research suggested that lutein could be a promising candidate for breast cancer chemoprevention, with HES1 potentially playing a crucial role in mediating lutein’s suppression of hypoxia-induced, ROS-driven breast cancer progression." (PMID 39918669, 2025). "Therefore, Hes1 is a core regulatory factor in the development and treatment resistance of breast cancer, and targeting Hes1 and its related pathways may provide new strategies for precision treatment of breast cancer." (PMID 40755759, 2025). "Indeed, the knock-down of HES1 induced PARP cleavage in all of the breast cancer cell lines tested." (PMID 30952976, 2019). "Another study showed that Hes1 might modulate the therapeutic resistance in breast cancer." (PMID 26452029, 2015). "Furthermore, we detected cleaved Notch1 and Hes1/5 in early precursors of breast cancers - hyperplasia and ductal carcinoma in situ - suggesting that aberrant Notch activation may be an early event in breast cancer progression." (PMID 20030805, 2009). "In HER2-overexpressing SKBR3 breast cancer cells with trastuzumab resistance, STAT3/HIF-1α axis-mediated Hes1 induction downregulates PTEN, positioning Hes1 as a pivotal node linking STAT3 signaling to PTEN suppression." (PMID 40755759, 2025).